IL6 (interleukin 6)
Diseases named in the same sentence as IL6 in open-access papers (continued):
Sharing a sentence is not in itself a finding about the gene and the disease.
tumor (continued). "The results of GSVA enrichment analysis revealed that SH3D21 positive HCC cells exhibited enrichment in the different pathways associated with tumor proliferation, invasion, and immunosuppression, such as PI3K/AKT/mTOR, angiogenesis, EMT, IL6-JAK-STAT3." (PMID 40179068, 2025). "Currently, it is believed that tumor cells produce a significant amount of pro-inflammatory cytokines, including IL-1β and IL-6, as they adapt to the surrounding environment." (PMID 40959570, 2025). "It promotes Th17-type immune responses and the synthesis of IL-6 and IL-17, which helps in creating a tumor-supportive microenvironment." (PMID 40801650, 2025). "Our data indicated that treatment with quadrigemine I significantly reduced the secretion of key pro-inflammatory cytokines, such as TNF-α, IL-6, and IL-1β, in various tissues, including serum, liver, spleen, and tumor tissues." (PMID 40429988, 2025). "This enhanced interaction leads to increased STAT3 and NF-κB activity, thereby promoting tumor cell proliferation through IL-1 and IL-6." (PMID 40562773, 2025). "TIM-3 promotes tumor progression by inducing the macrophage migration and tumor-promoting M2 polarization via the IL-6/NF-κB pathway." (PMID 40895574, 2025). "The senescence-associated secretory phenotype (SASP), which consists of a group of factors secreted by senescent cells, including IL-6, IL-8 and growth factors, has the potential to promote tumour growth and metastasis in the tumour microenvironment." (PMID 40556831, 2025). "In contrast, a study that assessed IL6 levels in LUSC tumor tissue showed moderate to high IL6 levels in tumor cells and cancer-associated fibroblasts, findings that substantiate IL6 in vivo relevance." (PMID 41304808, 2025). "It has been shown that proinflammatory cytokines released by immunological or tumour cells during CC, such as interleukin‐6 (IL‐6), tumour necrosis factor‐α (TNF‐α) and interleukin‐1 (IL‐1), cause muscle atrophy by activation of NF‐κB pathways." (PMID 40170230, 2025). "In ESCC, it was discovered that IL-6 regulated the immunosuppressive tumor microenvironment, partially explaining the poor reaction of immunotherapy in patients with elevated IL-6 levels." (PMID 40433391, 2025). "The results showed a significant increase in tumor cell apoptosis after combined IL-6 and PD1 blockade." (PMID 40040705, 2025). "IL-6 also influences multiple tumor-related mechanisms, such as apoptosis inhibition, enhancement of cell proliferation, migration, invasion, neovascularization, and metastasis." (PMID 40869161, 2025). "Tumor-derived and systemic factors, most notably IL-6, tumor-secreted PTHrP, and ZAG, transactivate thermogenic gene expression in different adipose tissue depots, resulting in the browning process." (PMID 40869331, 2025). "IL‐6 promotes tumor cell proliferation, survival, and migration by activating the STAT3 signaling pathway." (PMID 40040540, 2025). "IL-6, in turn, can facilitate tumor progression through various mechanisms, including the promotion of inflammatory responses, the upregulation of key proteins involved in tumor proliferation and migration, and the activation of the STAT3 pathway." (PMID 41403696, 2025). "The NF-κB signaling pathway plays a key role in promoting pro-inflammatory cytokines, such as TNF-α, IL-1β, and IL-6, which are involved in tumor initiation and progression." (PMID 41154100, 2025). "Third, TA-MSCs enhance tumor vascularization by stimulating adjacent macrophages to produce pro-angiogenic factors like IL-6, IL-8, and VEGF." (PMID 40676710, 2025). "For example, the prognostic weight of CLR is conceptually consistent with the well-documented roles of its components: CRP, an acute-phase reactant driven by pro-inflammatory cytokines like IL-6, and lymphocytes, essential for adaptive anti-tumor immunity." (PMID 41451214, 2025).
tumor (continued). "Further, compared to the oe‐NC+M2pep‐Cs NPs/Plerixafor group, the expression of IFN‐γ, IL‐12, and IL‐6 was significantly reduced in the tumor tissues of mice in the oe‐CXCR4+M2pep‐Cs NPs/Plerixafor group." (PMID 40536774, 2025). "The IL-6/JAK1/STAT3 signal axis is implicated in promoting inflammatory responses and cellular proliferation, thereby influencing the tumor microenvironment and potentially exacerbating the susceptibility to gastric carcinogenesis." (PMID 41284643, 2025). "The concentrations of immune‐promoting Th1 cytokines (IFN‐γ, TNF‐α, and IL‐2) as well as proinflammatory signal (IL‐6) determined in culture supernatants and tumor tissues were evidently higher in N@VP + 2 Gy group." (PMID 40231790, 2025). "A key mechanism involves the chronic inflammatory tumor microenvironment, where malignant B cells and stromal components release cytokines (e.g., IL-6, TNF-α), chemokines, ROS, and growth factors." (PMID 41516229, 2025). "A large-scale adjuvant KIRC trial has identified IL6 as a pivotal constituent within the tumor-enriched molecular signaling pathway." (PMID 40612864, 2025). "Functionally, the expression of SPINK1 is upregulated by inflammatory signals from the tumor microenvironment, particularly interleukin-6 (IL-6) Via the STAT3 pathway." (PMID 41465391, 2025). "Mechanistic studies revealed that Butein markedly downregulated the protein and mRNA expression of TWEAK, FN14, and TRAF1/2 in tumor tissue, and decreased serum levels of NF-κB-related inflammatory factors, including IL-1β, IL-6, IFN-γ, and TNF-α." (PMID 41458609, 2025). "The anti-histamine drug ketotifen effectively induces apoptosis of NEPC tumor cells by targeting the interleukin-6 (IL-6)/signal transducer and activator of transcription 3 (STAT3) pathway, which reduces the survival rate of NEPC." (PMID 40746825, 2025). "The enrichment of cancer stem cells (CSCs) within tumours is often driven by upregulation of IL-6 secretion via Stat3 pathway." (PMID 40414892, 2025). "In UBC cases, as with other common cancers, a higher NLR correlates with higher IL-6 and IL-8 levels, higher IL-8 levels correlated with greater neutrophil infiltration into the tumor, and greater Treg numbers in UBC." (PMID 40149682, 2025). "mRNA expression analysis showed the upregulation of apoptosis-related genes (p16INK4a, p21CIP1) alongside enhanced anti-tumor immune responses (IL-6, IL-8) in the affected tissue samples." (PMID 40573301, 2025). "In liver metastases, TGF‐β and IL‐6 can deliver signaling to the liver and promote the enrichment of intermediate clusters associated with fibronectin and SPP1 expression, and induce tumor‐specific T cell exhaustion." (PMID 41176774, 2025). "Interleukin-6 (IL-6) and interleukin-8 (IL-8) are cytokines that play significant roles in immune response, inflammation, and tumor biology." (PMID 40573301, 2025). "Tumor-derived IL-6 disrupts the blood-brain barrier and enters the central nervous system, activating the area postrema (AP)-parabrachial nucleus (PBN) pathway." (PMID 41142779, 2025). "Targeting the signaling pathways responsible for the differentiation and expansion of MDSCs, such as those mediated by tumor-secreted factors like GM-CSF, IL-6, and VEGF, can block MDSC development and maturation." (PMID 39930476, 2025). "This activation drives the secretion of pro-inflammatory cytokines such as IL-6 and IL-8, exacerbating chronic inflammation in the tumor microenvironment, thereby facilitating tumor progression and immune evasion." (PMID 40755775, 2025). "The results showed that IRFA significantly up-regulated TNF-α and IL-6 at the residual tumor site by 31-fold and 28-fold compared with NC, respectively." (PMID 39882403, 2025). "ROS-mediated activation of NF-κB leads to the production of pro-inflammatory cytokines such as TNF, IL-1β, and IL-6, which further drive tumor-promoting inflammation." (PMID 41071399, 2025).
tumor (continued). "Proinflammatory cytokines, such as tumor necrosis factor-alpha (TNF-α), interleukin-1 beta (IL-1β), and interleukin-6 (IL-6), play a crucial role in shaping a proinflammatory tumor microenvironment." (PMID 40002704, 2025). "In IL-6 knockout mice, infiltrating macrophages never developed a predominant M2 phenotype, suggesting that IL-6 promotes alternative activation of macrophages and that TAMs increase the tumor-initiating ability by secreting IL-6." (PMID 40723226, 2025). "IL-12 was positively correlated with ECOG (r = 0.190, p<0.05), AFP (r = 0.247, p<0.05) and intrahepatic tumor size (r = 0.230, p<0.05), and IL-6 was positively correlated with intrahepatic tumor size (r = 0.217, p<0.05)." (PMID 40568585, 2025). "All of above indicate that IL-6 is not only a target for tumor control but also a contributor to irAEs." (PMID 40519900, 2025). "The main sources of IL-6 in the tumor microenvironment are tumor cells, stromal cells and infiltrating immune cells." (PMID 40255422, 2025). "Same as pamidronate, but 100 times as potent.Additionally, has in vitro direct anti-tumor effects by down-regulating IL-6 secretion and reducing CD40, CD49d, CD54, and CD106 expression." (PMID 40862742, 2025). "We found a decreased proportion of Type I tumors in patients with high IL-6 compared to those with low IL-6 when the tumor microenvironment in ESCC TMAs was classified." (PMID 40433391, 2025). "Targeting the IL-6/IL-6R/ERK pathway emerges as a promising therapeutic approach for combating CAF-driven tumour progression and improving clinical outcomes in patients with aggressive, therapy-resistant HNSCC." (PMID 39858048, 2025). "The serum of LLC tumor-bearing mice exhibited a 2.5-fold increase in IL-6 compared to that of the control group, while administering a low dose of DTT water extract reduced serum IL-6 by 1.8-fold (relative to the control level)." (PMID 41226740, 2025). "Overexpression of MLKL upregulates CD47 expression via IL-6 signaling, which consequently suppresses macrophage phagocytosis and enhances tumor immune evasion." (PMID 41267084, 2025). "Noticeably, tumor cells produce high levels of interleukin-6 (IL-6), which lower the synthesis of muscle proteins and enhance muscle wasting." (PMID 40181329, 2025). "A recent study has shown that upregulation of fibroblast monoamine oxidase A in the tumor stroma induces the tumorigenic phenotype of fibroblasts and promotes PCa cell proliferation and stemness marker expression of PCSCs through the IL-6/STAT3 pathway." (PMID 39711287, 2025). "IL-1 has been reported to promote tumor growth by inducing the expression of inflammatory mediators, including IL-6 and COX2, which support cell survival and proliferation." (PMID 40565234, 2025). "Simultaneously F. nucleatum develops a pro-tumorigenic microenvironment by recruiting immune cells and promoting the synthesis of pro-inflammatory cytokines like IL-6 and TNFα, hence supporting tumor growth and enabling immune evasion." (PMID 40801650, 2025). "TAM, on the other hand, promotes the activation of CAF and enhances the aggressiveness of tumor cells by producing molecules such as IL-6, CXCL12, and TGF-β." (PMID 40370720, 2025). "Previous studies have demonstrated that tumor cells secrete cytokines, including IL-6 and CXCL3, among others, to facilitate the recruitment of MDSCs into the TIME." (PMID 41326342, 2025). "At the same time, CAFs in the tumor microenvironment activate STAT3 signaling by secreting IL-6, promoting the maintenance of stemness and immune escape of resistant clones, driving clonal evolution." (PMID 41293424, 2025). "In most cases, IL‐6 plasma levels were below the sensitivity threshold of the ELISA kit for IL‐6 detection even before the surgical removal of the tumor." (PMID 40831233, 2025). "All extracts significantly inhibited cell proliferation and IL-6 secretion, underscoring their potential to modulate tumor-related inflammation." (PMID 41302458, 2025).
tumor (continued). "For example, IL‐6 is proven to recruit myeloid‐derived suppressor cells (MDSCs) to the tumor site, which are reported to block immune surveillance by suppressing CD8+ T cells and NK cells." (PMID 39811803, 2025). "IL-6, produced by both tumour and stromal cells, not only enhances cancer stem cell (CSC) proliferation but is also a key mediator of systemic inflammation, which is correlated with poor prognosis in CCA patients." (PMID 40861435, 2025). "Meanwhile, anti-cytokine therapies, such as infliximab, which blocks tumor necrosis factor (TNF), or siltuximab, which targets IL-6, intervene in tumor progression by inhibiting pro-tumorigenic cytokines." (PMID 40136462, 2025). "IL-6 mediates key interactions in the tumor microenvironment that drive the progression of multiple cancers." (PMID 41293238, 2025). "Inflammatory factors such as IFN-γ, TNF-α, IL-6, and IL-12 have been shown to enhance the body’s anti-tumor response." (PMID 41383334, 2025). "Previous studies have implicated the MAPK signaling pathway in mediating the production and activation of cytokines, including IL-6 and IL-8, which subsequently impact tumor cell survival and immune cell recruitment." (PMID 39972459, 2025). "In the case of low miR-21-5p expression, inflammatory infiltration decreased and fewer tumor-associated inflammatory cytokines, such as TNF-α, IL-6, IL-17A and IL-21, were produced." (PMID 40535722, 2025). "In breast cancer, IL-6, a major inflammaging cytokine, has been identified as a driver of tumor progression, with high serum levels correlating with poor prognosis." (PMID 41281748, 2025). "This procedure elevates the concentration of IL-6 in the bloodstream, hence facilitating the progression of tumor growth." (PMID 39802656, 2025). "In a preclinical cerebellopontine schwannoma mouse model, treatment with an angiotensin‐receptor blocker (losartan) as an anti‐fibrotic through inhibition of IL‐6/STAT3 and TGF‐β, reduced the amount of collagen I and prevented tumor‐induced hearing loss." (PMID 39506612, 2025). "High level of IL-6 was correlative with tumor proliferation, poorer chemoimmunotherapy efficacy and worse survival outcomes." (PMID 40160826, 2025). "Kaempferol can also significantly reduce the expression of interleukin 6 and interleukin 1B, and exhibits a dose dependence, thereby alleviating the degree of breast hyperplasia." (PMID 40550087, 2025). "This creates a self-sustaining IL-6/STAT3 positive feedback loop that amplifies tumor-promoting inflammation." (PMID 41356485, 2025). "TA-MSCs release tumor-promoting inflammatory cytokines and chemokines, including IL-6, IL-8, VEGF, and SDF-1, enhancing their oncogenic characteristics." (PMID 40676710, 2025). "Patients were categorized into groups with low and high IL-6 levels depending on the median IL-6 expression in tumor tissues." (PMID 40433391, 2025). "IL-6 can promote tumor cell survival and proliferation but can also activate immune cells in certain contexts." (PMID 40375990, 2025). "The expression of IDO1 can be triggered as a counter-regulatory response to cytokines released by tumor-infiltrating immune cells (such as IL-1β and IL-6), and can also be maintained through intrinsic oncogenic signaling in the tumor." (PMID 40137165, 2025). "IL-6 is a significant and abundant cytokine in the tumor microenvironment, produced by malignant tumor cells that stimulate cancer-related inflammation and promote stem cell proliferation." (PMID 40869207, 2025). "Analysis of the database revealed that IL-6 was positively correlated with angiogenesis, tumor inflammatory signaling, apoptosis, Pentose/phosphate/pathway, PI3K/AKT/mTOR pathway, and P-53 pathway." (PMID 40040705, 2025). "In the tumor microenvironment, IL-6 has widely been described as a cytokine that acts as a growth factor for cancer cells, promoting tumorigenesis." (PMID 40696387, 2025).
tumor (continued). "It promotes the expression of IL-6, which not only facilitates tumor proliferation and survival but also modulates immune evasion." (PMID 40429961, 2025). "Another function includes upregulating pro-inflammatory genes cyclooxygenase-2 (COX-2) and IL-6, creating a tumor-suppressive and pro-inflammatory microenvironment." (PMID 39921821, 2025). "We found that PRDX1 deletion in macrophages reduced IL‐6 levels, thereby inhibiting tumor growth and enhancing antitumor immunity." (PMID 41306557, 2025). "Our analyses revealed a significant association between elevated Fusobacterium nucleatum levels and increased tumor expression of the pro-inflammatory cytokines IL-6 and IL-17 (both p = 0.02)." (PMID 41267807, 2025). "Clinically, this synergy underscores the need for dual therapeutic strategies targeting both inflammation (e.g., anti-IL-6 agents) and tumor metabolism (e.g., glycolysis inhibitors)." (PMID 40342817, 2025). "Inhibiting IL6 signaling can disrupt these survival pathways, potentially sensitizing tumor cells to chemotherapy and reducing resistance." (PMID 40427188, 2025). "M2 macrophage polarization and enhanced IL-6 expression drive tumor progression, highlighting their crucial role in shaping the TME across various cancers." (PMID 40103824, 2025). "Mechanistically, its action is not only due to direct apoptosis induction but also due to immunosuppressive myeloid cell depletion and inhibition of interleukin 6 (IL-6)/IL-23/IL-17-mediated pro-tumor inflammation." (PMID 41293269, 2025). "Lactate induces histone lactylation in macrophages, repressing anti‐tumor genes (e.g., RARγ) while activating the transcription of immunosuppressive IL‐6." (PMID 40904700, 2025). "Their plasticity, often driven by tumor-derived IL-6, makes them adaptable and resistant to therapy." (PMID 41311372, 2025). "IL-6, in particular, acts as a pleiotropic cytokine that fosters tumor growth through the STAT3 signaling pathway and enhances neutrophilic infiltration." (PMID 41180708, 2025). "Lastly, Tregs secrete tumor-promoting cytokines such as TGF-β, IL-10, and IL-6, whereas tumor-suppressing CD8+ and NK cells secrete IFN-γ, TNF-α, etc.." (PMID 41369383, 2025). "IL-6 maintains a pro-tumor environment by supporting angiogenesis and tumor evasion of immune surveillance." (PMID 40568973, 2025). "Neutrophil and platelets can stimulate cancer progression by producing vascular endothelial growth factor (VEGF) and interleukin-6 to enhance tumor angiogenesis and tumor cell epithelial-mesenchymal transition." (PMID 40297178, 2025). "To further confirm that KCs are induced by tumor cell-derived exosomes and secrete IL6, we determined the expression of IL6 and markers of M1-like macrophages and TAMs by RT-PCR." (PMID 39744421, 2025). "EMT is strongly regulated by immunological factors, including pro-inflammatory cytokines (e.g., TNF-α, IL-6) and signals from the tumor microenvironment, such as TGF-β and chemokines." (PMID 40362280, 2025). "Tumor tissues can induce a systemic inflammatory response by secreting pro-inflammatory cytokines such as interleukin-6 (IL-6) and interleukin-1β (IL-1β), which stimulate bone marrow activity and lead to increased platelet production." (PMID 40837560, 2025). "One mechanism is by inducing IL-6 trans-signalling by shedding sIL-6R, a process particularly important in KRas-mutant cancers, where it promotes tumour growth and progression, contributing to resistance against EGFR-targeted therapies." (PMID 40427200, 2025). "This activation leads to the upregulation of pro-inflammatory cytokines, such as TNF-α and IL-6, contributing to development of the microenvironment that promotes tumor cell adhesion and invasion." (PMID 41050662, 2025). "The present study demonstrated that the expression of interleukin-6 (IL-6) in the tumor tissue was significantly higher than in the adjacent tissue." (PMID 41007818, 2025).